KCNN4 (potassium calcium-activated channel subfamily N member 4)
Description:
Intermediate conductance calcium-activated potassium channel that mediates the voltage-independent transmembrane transfer of potassium across the cell membrane through a constitutive interaction with calmodulin which binds the intracellular calcium allowing its opening. The current is characterized by a voltage-independent activation, an intracellular calcium concentration increase-dependent activation and a single-channel conductance of about 25 picosiemens. Also presents an inwardly rectifying current, thus reducing its already small outward conductance of potassium ions, which is particularly the case when the membrane potential displays positive values, above + 20 mV. Controls calcium influx during vascular contractility by being responsible of membrane hyperpolarization induced by vasoactive factors in proliferative vascular smooth muscle cell types (By similarity). Following calcium influx, the consecutive activation of KCNN4 channel leads to a hyperpolarization of the cell membrane potential and hence an increase of the electrical driving force for further calcium influx promoting sustained calcium entry in response to stimulation with chemotactic peptides. Required for maximal calcium influx and proliferation during the reactivation of naive T-cells. Plays a role in the late stages of EGF-induced macropinocytosis through activation by PI(3)P.
Synonyms: SKCa4; hSK4; hIK1; IK1; IKCA1; KCA4; SK4; KCa3.1; hKCa4; hIKCa1; IK; DHS2
Tractability: Small molecule: an approved drug acts on it; a structure with a bound ligand is known; a high-quality ligand is known; it belongs to a druggable protein family. Antibody: UniProt places it where antibodies can reach, with high confidence; its Gene Ontology location is reachable by antibodies, with high confidence; UniProt predicts a signal peptide or a membrane-spanning region. PROTAC: ubiquitination databases record sites on it; a small molecule that binds it is known.
Target class: Voltage-gated ion channel; Ion channel; Calcium-activated potassium channel; Potassium channels
Chemical probes: TRAM-34 (high quality)
Safety:
Unwanted effects reported when the protein is acted on. In parentheses: how it was acted on, where the effect was seen, and who reports it.
ataxia (activation, acute dosing; central nervous system, cardiovascular; source: Lynch et al. (2017))
convulsions (inhibition, acute dosing; central nervous system, cardiovascular; source: Lynch et al. (2017))
decreased convulsions (activation, acute dosing; central nervous system, cardiovascular; source: Lynch et al. (2017))
decreased locomotor activity (activation, acute dosing; central nervous system, cardiovascular; source: Lynch et al. (2017))
increased atrial refractory period (inhibition, acute dosing; central nervous system, cardiovascular; source: Lynch et al. (2017))
neurotoxicity (inhibition, acute dosing; central nervous system, cardiovascular; source: Lynch et al. (2017))
Gene: Protein-coding gene on chromosome 19 (43,766,517 to 43,781,021, reverse strand). Ensembl gene ENSG00000104783.
Subcellular location: Cell membrane; Cell projection, ruffle membrane
Subcellular location (Human Protein Atlas): Cytosol; Plasma membrane
Pathways (Reactome):
Neuronal System: Ca2+ activated K+ channels
Gene Ontology:
Molecular function: calcium-activated potassium channel activity; calmodulin binding; intermediate conductance calcium-activated potassium channel activity; protein binding; protein homodimerization activity; protein phosphatase binding; potassium channel activity; small conductance calcium-activated potassium channel activity
Biological process: calcium ion transport; macropinocytosis; positive regulation of T cell receptor signaling pathway; potassium ion transmembrane transport; protein homotetramerization; regulation of calcium ion import across plasma membrane; stabilization of membrane potential; defense response; positive regulation of potassium ion transmembrane transport; potassium ion transport; positive regulation of transport
Cellular component: plasma membrane; ruffle membrane; vesicle; neuron projection; neuronal cell body; voltage-gated potassium channel complex; membrane
Genetic constraint (gnomAD): Loss-of-function variants: 30 observed, 41.86 expected, observed/expected ratio (o/e) 0.72, 90% interval 0.54 to 0.97. The upper end of that interval is the gene's LOEUF score, 0.97, which puts it in group 4 of 6, group 1 being the genes least tolerant of losing a copy. Missense variants: 463 observed, 567.56 expected, observed/expected ratio (o/e) 0.82, 90% interval 0.75 to 0.88. Synonymous variants: 231 observed, 251.08 expected, observed/expected ratio (o/e) 0.92, 90% interval 0.83 to 1.03.
Homologues: Orthologues: chimpanzee KCNN4 (99% identical), macaque KCNN4 (98% identical), pig KCNN4 (90% identical), mouse Kcnn4 (87% identical), guinea pig KCNN4 (86% identical), rat Kcnn4 (85% identical), rabbit KCNN4 (79% identical), dog KCNN4 (77% identical), tropical clawed frog kcnn4 (52% identical), zebrafish kcnn4 (48% identical), Drosophila melanogaster SK (42% identical), Caenorhabditis elegans kcnl-2 (36% identical), and 3 more. Paralogues in human: KCNN3 (44% identical), KCNN1 (44% identical), KCNN2 (44% identical).
Diseases named in the same sentence as KCNN4 in open-access papers:
KCNN4 is named in the same sentence as 208 diseases in open-access papers, as found by Europe PMC text mining. Sharing a sentence is not in itself a finding about the gene and the disease. The quoted sentences say what the papers report.
glioblastoma (41 papers, 2012 to 2026). The most malignant astrocytic tumor (WHO grade IV). "It has been reported that KCNJ10, KCNA5, and KCNN4 can affect the proliferation and invasive ability of gliomas and glioblastomas by altering the cell membrane potential in excitatory cell-derived tumors." (PMID 38905316, 2024). "In one report, the potassium intermediate-small conductance calcium-activated channel, superfamily N, member 4 (KCNN4, also known as KCa3.1), was investigated to elucidate an important role in the ability of glioblastoma cells to infiltrate brain tissues." (PMID 37103862, 2023). "Consistently, KCa3.1 (KCNN4) mRNA abundance of primary glioblastoma stem cells correlated with mesenchymal marker expression and in vitro matrix invasion capability in our previous work." (PMID 37996600, 2023). "Within the potassium intermediate/small conductance calcium-activated channels, expression of 3 genes (namely KCNE3, KCNE4, KCNN4) has been found altered in the current study, namely in glioblastoma and lung adenocarcinoma." (PMID 27716384, 2016). "KCa3.1, encoded by Potassium Calcium-Activated Channel Subfamily N Member 4 (KCNN4), has been reported to be highly expressed in various cancers including HCC, affecting cell metabolism, and reducing cell motility in glioblastoma derived CSCs." (PMID 35805963, 2022). "Thus, changes in glioblastoma REST levels could explain the ERK-independent Kcnn4 transcriptional downregulation we found in GL-15 glioblastoma cells with time of culture." (PMID 22675627, 2012). "In particular, radiation-stimulated activation of Ca2+-dependent high conductance BK (KCa1.1, KCNMA1) and intermediate conductance IK (KCa3.1, SK4, KCNN4) K+ channels occurs in glioblastoma cells." (PMID 32390841, 2020).
glioma (36 papers, 2012 to 2025). A benign or malignant brain and spinal cord tumor that arises from glial cells (astrocytes, oligodendrocytes, ependymal cells). "The REMBRANDT database shows that the gene KCNN4, which encodes the KCa3.1 channel, is overexpressed in more than 30% of gliomas, and its expression is associated with a poor prognosis." (PMID 30274242, 2018). "The REepository of Molecular BRAin Neoplasia DaTa (REMBRANDT) database identified the gene KCNN4, which encodes for KCa3.1, as being over-expressed in 32% of glioma patients and correlating with significant shortened survival." (PMID 27096953, 2016). "It was reported that KCNN4 regulated calcium ion signals to influence the cell cycle arrest and promote the repair of damaged DNA in glioma, thereby increasing the radio-resistance of tumors." (PMID 37328854, 2023). "The gene encoding KCa3.1, KCNN4, is overexpressed in 32% of gliomas and correlates with shorter survival." (PMID 33050088, 2020).
breast carcinoma (32 papers, 2013 to 2025). "Fifteen variants (tagging 14 genes including KCNN4) were identified with pleiotropic association with breast cancer." (PMID 38893190, 2024). "Rather, at the germline level, several intronic KCNN4 single nucleotide polymorphisms (SNPs) have been shown to alter women's breast cancer risk in general and particularly of ER‐positive breast cancer." (PMID 28557306, 2017). "Likewise, rs3760982 (1.1kb 5′ of KCNN4 on chromosome 19q13.31) is associated with breast cancer susceptibility and we find that its A allele is predicted to enhance RUNX binding." (PMID 28957321, 2017). "Among other K+ channels, the Ca2+-activated K+ channel (KCa) subfamily members of the big (BK) and intermediate (IK aka IKCa, KCNN4, KCa3.1 or SK4) type have been proposed as therapeutic targets in breast cancer (BC)." (PMID 36302750, 2022). "At the tumor level, the degree of KCNN4 mRNA expression is potentially useful to stratify breast cancer patients into those with shorter and longer survival time." (PMID 30658505, 2019). "Low expression of KCNN4 indicated poor survival of breast cancer patients." (PMID 35326596, 2022). "Furthermore, among 150 breast cancer risk regions identified by genome-wide association studies, several ERGs identified in this study (BARX2, CBX6, KCNN4, MYEOV, PDZK1 in 300 ERGs) were included as the targets for cancer drivers, transcription factors, and signaling proteins." (PMID 35976950, 2022). "Survival analysis of ion channels interacting with EMT-related genes showed KCNN4 (p-value: 0.071), CFTR (p-value: 0.16), KCNJ10 (p-value: 0.17), VDAC1 (p-value: 0.000003) and VDAC2 (p-value: 0.052) the level of expression associated with survival of breast cancer patients." (PMID 35326596, 2022). "Many studies have shown that potassium channels, including KCNN4, KCNA1, Kv11.1, KCNK9, KCNE1, and GIRK1 are involved in the regulation of malignant breast cancer transformation." (PMID 34195184, 2021). "The PsePDC-DTIs model provides us with 10 potential DTIs for breast cancer treatment, among which erlotinib (DB00530) and FGFR2 (hsa2263), caffeine (DB00201) and KCNN4 (hsa3783), as well as afatinib (DB08916) and FGFR2 (hsa2263) are found with direct or inferred evidence." (PMID 34946556, 2021).
sickle cell disease (24 papers, 2011 to 2025). Sickle cell anemias are chronic hemolytic diseases that may induce three types of acute accidents: severe anemia, severe bacterial infections, and ischemic vasoocclusive accidents (VOA) caused by sickle-shaped red blood cells obstructing small blood vessels and capillaries. "KCNN4 gain-of-function mutations cause the autosomal dominant hemolytic anemia, hereditary xerocytosis, and KCa3.1 inhibition attenuates some indices of disease severity in murine and human sickle cell disease." (PMID 41122971, 2025). "In sickle cell anemia, KCNN4 activation induces catastrophic and irreversible dehydration causing the precipitation of hemoglobin within the cells, and in malaria, a degree of dehydration makes it difficult for the malarial parasite to multiply within the RBC, limiting its cycle." (PMID 39716493, 2024). "The RBC dehydration in sickle cell anemia is caused by facilitated K+ loss through hyperactivated KCNN4 (also known as the Gardos Channel in RBCs) and K+-Cl- cotransporter that is not compensated by uptake of equal amounts of Na+." (PMID 29910743, 2018). "In addition, the KCNN4 (or Gardos channel) blocker senicapoc (ICA-17043) has recently been tested in sickle cell disease." (PMID 29910743, 2018). "Whereas the physiological role of KCNN4 in RBC is still largely ignored, it is involved in two major RBC diseases: sickle cell anemia and malaria." (PMID 39716493, 2024). "In sickle cell disease, KCNN4 (or known as the Gardos channel in RBCs) is activated by two pathways." (PMID 29910743, 2018).
melanoma (23 papers, 2011 to 2025). A malignant, usually aggressive tumor composed of atypical, neoplastic melanocytes. "On the other hand, several metastatic lines—including IGR37—regained significant expression of TRPM1 and showed reduced expression of KCNMA1, KCNN4, and TRPM2, compared to the primary melanoma lines (third row)." (PMID 34445066, 2021).
atherosclerosis (21 papers, 2012 to 2025). A disease characterized by the build-up of fatty material and calcium deposition in the arterial wall resulting in partial or complete occlusion of the arterial lumen. "Our findings provide novel evidence that NOX5-derived ROS increase functional expression of KCNN4 through activator protein-1, providing another potential link between NOX, CSMC phenotypic modulation, and atherosclerosis." (PMID 25144362, 2014). "Inhibition of the bFGF-induced increase in KCNN4 mRNA, protein, and channel activity by treatment with Apo indicates a critical role for NOX in KCNN4 regulation and provides a novel pathway for NOX to contribute to the progression of atherosclerosis." (PMID 25144362, 2014). "Given the central role of KCNN4 in phenotypic modulation and neointimal formation and the recently described role of NOX5 in human SMC proliferation and atherosclerosis, we tested the hypothesis that NOX5 is required for transcriptional upregulation of KCNN4 through AP-1." (PMID 25144362, 2014). "Studies have shown that KCNN4 upregulation is required for mitogen-induced suppression of SMC markers as well as vascular SMC migration and proliferation, and has been shown to occur during atherosclerosis and restenosis indicating these channels play a key role in coronary plaque formation." (PMID 25144362, 2014). "The novel findings of our study, combined with results from previous studies showing KCNN4 plays a key role in regulating SMC phenotypic modulation and post-angioplasty restenosis, strongly support a role for NOX5 regulation of KCNN4 in the development of atherosclerosis and restenosis." (PMID 25144362, 2014).
pancreatic cancer (21 papers, 2012 to 2025). "In the present study, we aimed to gain useful information about the interacting partners of KCa3.1 encoded by KCNN4, specifically in pancreatic cancer." (PMID 40952239, 2025). "Analogous to CCR4, the upregulated KCNN4 expression is associated with adverse prognosis in numerous malignancies, including papillary thyroid carcinoma, pancreatic cancer, and ccRCC." (PMID 41301871, 2025). "This increase is clearly observed in both bulk RNA‐seq data from TCGA and Gene Chip analyses, thus reinforcing the hypothesis that KCa3.1 encoded by KCNN4 plays a relevant role in pancreatic cancer progression in humans." (PMID 40952239, 2025). "The role of KCNN4 in regulating oxygen consumption and ATP production has been confirmed in a subset of Pancreatic carcinoma cell lines, but metabolic regulation of KCNN4 in the progression of other cancers has not been reported." (PMID 35805963, 2022). "In this paragraph, we describe some of these effects on KCNN4 expression as they have been reported for a number of different cancer types including breast, lung, endometrial, and pancreatic cancer." (PMID 30658505, 2019). "Analysis of TCGA‐PAAD RNA‐seq data reveals that KCNN4 expression is significantly elevated in pancreatic tumor samples compared to normal tissues (p < 3.36e−26), and also shows increased expression in tumors with nodal metastasis compared to non‐metastatic tumors." (PMID 40952239, 2025). "It is recommended that future research efforts concentrate on ascertaining whether KCNN4‐directed therapies can effectively modulate the immune microenvironment, with the objective of enhancing immune activation and tumor control in pancreatic cancer." (PMID 40952239, 2025). "The other selected genes are HIST1H1E, LRAT, LCN2, KCNN4, RHOU, and EPHA5 in the order of them entering the model, among which LRAT, LCN2, RHOU, and EPHA5 are known to link to prostate cancer, and HIST1H1E and KCNN4 are connected to myeloma and pancreatic cancer, respectively." (PMID 29100492, 2017). "Analysis of the expression level of the hub genes indicated that the genes TNNT1, KCNN4, SH2D3A, and PHLDA2 were differentially expressed between 179 pancreatic tumors and 171 normal tissue samples." (PMID 35712127, 2022). "The expression level of genes TNNT1, KCNN4, SH2D3A, and PHLDA2 was significantly different between the 179 pancreatic tumors and 171 normal tissue samples." (PMID 35712127, 2022). "We investigated the expression of these potential oncogenes (MYEOV, KCNN4, FAM83A, S100A16, and DDX60L) in the pancreatic cancer cell lines of the Cancer Cell Line Encyclopedia (CCLE) database." (PMID 34789165, 2021). "Research reveals that GABRP orchestrates tumor microenvironment remodeling in pancreatic cancer by modulating KCNN4-dependent calcium ion flux, a mechanism independent of GABA transmission." (PMID 40901676, 2025). "Interestingly, the five genes identified in this study (DDX60L, FAM83A, KCNN4, MYEOV, and S100A16) showed some similar characteristics; they were highly expressed and corelated with poor prognosis in pancreatic cancer." (PMID 34789165, 2021). "The results showed that MYEOV, KCNN4, S100A16, and DDX60L are highly expressed in most pancreatic cancer cell lines, but FAM83A is not." (PMID 34789165, 2021).
asthma (15 papers, 2011 to 2025). "Modulation of ENaC, CFTR, CaCC, KCNQ1 and KCNN4 ion channels by estrogen negatively affect airway surface liquid height and mucociliary clearance which impact on mucus production, bacterial virulence and airway inflammation, contributing to CF and asthma pathophysiology." (PMID 39026347, 2024).
prostate carcinoma (14 papers, 2013 to 2025). A carcinoma that arises from epithelial cells of the prostate gland. "Previous researches have revealed that KCNN4 channels regulate cell cycle progression and cell growth in human endometrial cancer and prostate cancer cells." (PMID 27713134, 2016). "Previous research has also revealed that KCNN4 channels regulate cell cycle progression and cell growth in human endometrial cancer and prostate cancer cells." (PMID 24885636, 2014).
pulmonary fibrosis (13 papers, 2013 to 2026). Chronic progressive interstitial lung disorder characterized by the replacement of the lung tissue by connective tissue, leading to progressive dyspnea, respiratory failure, or right heart failure. "KCNN4 promotes Smad2/3 signaling in IPF-derived fibroblasts, facilitating the differentiation of fibroblasts into myofibroblasts and promoting the formation of pulmonary fibrosis." (PMID 40149666, 2025).
Alzheimer disease (11 papers, 2012 to 2024). A progressive, neurodegenerative disease characterized by loss of function and death of nerve cells in several areas of the brain leading to loss of cognitive function such as memory and language. "Although KCNN4 has been reported to be associated with some diseases, including inflammatory bowel disease, Crohn’s disease, and Alzheimer’s disease, germline pathogenic variants in KCNN4 have only been shown to be associated with DHS227–30." (PMID 36864026, 2023). "KCNN4 contributes the pro-inflammatory activation of microglia, with blocking of this channel shown to improve CNS outcomes following traumatic brain injury and has been proposed as a potential therapeutic for microglia neurotoxicity in Alzheimer’s disease." (PMID 38879567, 2024).